P3H4 (prolyl 3-hydroxylase family member 4 (inactive))
Description:
Part of a complex composed of PLOD1, P3H3 and P3H4 that catalyzes hydroxylation of lysine residues in collagen alpha chains and is required for normal assembly and cross-linking of collagen fibrils. Required for normal bone density and normal skin stability via its role in hydroxylation of lysine residues in collagen alpha chains and in collagen fibril assembly.
Synonyms: LEPREL4; NOL55; SC65; NO55
Tractability: Antibody: UniProt predicts a signal peptide or a membrane-spanning region. PROTAC: ubiquitination databases record sites on it.
Gene: Protein-coding gene on chromosome 17 (41,801,944 to 41,812,750, reverse strand). Ensembl gene ENSG00000141696.
Subcellular location: Endoplasmic reticulum
Subcellular location (Human Protein Atlas): Endoplasmic reticulum; Vesicles
Gene Ontology:
Molecular function: collagen binding
Biological process: bone remodeling; collagen biosynthetic process; collagen fibril organization; peptidyl-lysine hydroxylation; synaptonemal complex assembly
Cellular component: endoplasmic reticulum; condensed nuclear chromosome; nucleolus; synaptonemal complex; catalytic complex
Genetic constraint (gnomAD): Loss-of-function variants: 47 observed, 51.03 expected, observed/expected ratio (o/e) 0.92, 90% interval 0.73 to 1.17. The upper end of that interval is the gene's LOEUF score, 1.17, which puts it in group 5 of 6, group 1 being the genes least tolerant of losing a copy. Missense variants: 585 observed, 578.72 expected, observed/expected ratio (o/e) 1.01, 90% interval 0.94 to 1.08. Synonymous variants: 256 observed, 247.6 expected, observed/expected ratio (o/e) 1.03, 90% interval 0.93 to 1.15.
Homologues: Orthologues: chimpanzee P3H4 (99% identical), macaque P3H4 (98% identical), pig P3H4 (92% identical), dog P3H4 (92% identical), mouse P3h4 (91% identical), rat P3h4 (91% identical), rabbit P3H4 (66% identical), guinea pig P3H4 (62% identical), tropical clawed frog p3h4 (59% identical), zebrafish p3h4 (52% identical), Caenorhabditis elegans Y73F8A.26 (23% identical). Paralogues in human: CRTAP (48% identical).
Diseases named in the same sentence as P3H4 in open-access papers:
P3H4 is named in the same sentence as 13 diseases in open-access papers, as found by Europe PMC text mining. Sharing a sentence is not in itself a finding about the gene and the disease. The quoted sentences say what the papers report.
bladder cancer (9 papers, 2018 to 2025). "When examining proteins overexpressed in major immune cell populations, we found that HAM/TSP IgG frequently targeted P3H4, a nucleolar protein associated with bladder cancer, across CD4+, CD8+, and γδ T cell populations." (PMID 41303346, 2025). "It was confirmed that P3H4 expression associates with poor prognosis in bladder cancer." (PMID 37601252, 2023). "Moreover, high P3H4 expression was associated with aggressive clinicopathological features in bladder cancer." (PMID 30322400, 2018). "In bladder cancer, we screened seven hub genes (ACLY, CNP, NKIRAS2, P3H4, PDIA6, VPS25 and XPO1) associated with survival." (PMID 37601252, 2023). "Consistently, the inhibition of proliferation and invasion by the knockdown of P3H4 were also observed in bladder cancer." (PMID 34257701, 2021). "To further confirm the results, we analyzed the expression of P3H4 in 389 bladder cancer tissues and 19 adjacent normal tissues from the TCGA database." (PMID 30322400, 2018). "To examine the role of P3H4 in bladder cancer, we investigated the P3H4 expression in 44 primary tumors and their paired adjacent normal tissues using qRT-PCR." (PMID 30322400, 2018). "The mRNA expression of P3H4 was significantly related to several clinicopathological factors of bladder cancer, including age, race category, histologic grade, tumor histologic subtype, and AJCC stage." (PMID 30322400, 2018). "P3H4 was overexpressed in bladder cancer compared with the adjacent normal tissue both in our tissue samples and TCGA samples." (PMID 30322400, 2018). "We identified P3H4 as a tumor promotion gene in bladder cancer for the first time." (PMID 30322400, 2018). "Taken together, our findings suggest that P3H4 is involved in the progression of bladder cancer." (PMID 30322400, 2018). "To further explore whether P3H4 expression is related to clinicopathological factors of bladder cancer, we divided 389 patients with bladder cancer from the TCGA database into high P3H4 expression (n = 195) and low P3H4 expression (n = 194) groups according to the median value of P3H4." (PMID 30322400, 2018). "Given its tumorigenic role, P3H4 may serve as a promising tumor-promoting gene in bladder cancer." (PMID 30322400, 2018). "In bladder cancer, knockdown of P3H4 would result in arrested cell cycle and decreased expression levels of EMT-related proteins, suggesting that silence of P3H4 could efficiently inhibit the uncontrolled proliferation and invasiveness of bladder cancer." (PMID 34257701, 2021).
interstitial cystitis (3 papers, 2012 to 2022). A rare chronic debilitating urogenital disease characterized by urinary frequency, urgency, and pelvic pain. "The prolyl 3-hydroxylase family member 4 (P3H4, alias SC65) is a nucleoprotein originally identified as an autoantigen in interstitial cystitis." (PMID 35805016, 2022). "Prolyl 3-hydroxylase family member 4 (P3H4) is a nucleolar protein initially identified as an autoantigen in cases of interstitial cystitis." (PMID 30322400, 2018). "P3H4 is a nucleolar protein initially identified as an autoantigen in interstitial cystitis cases." (PMID 30322400, 2018).
lung adenocarcinoma (2 papers, 2021 to 2022). A carcinoma that arises from the lung and is characterized by the presence of malignant glandular epithelial cells. "Overexpression of P3H4 indicated a poor prognosis in lung adenocarcinoma." (PMID 35814377, 2022).
prostate carcinoma (2 papers, 2000 to 2019). A carcinoma that arises from epithelial cells of the prostate gland. "Although P3H4 has been reported as a tumor-associated auto-antigen in patients with prostate cancer, its biological functions in other cancers remain elusive." (PMID 31333338, 2019).
kidney cancer (1 paper, 2025). Primary or metastatic malignant neoplasm involving the kidney. "Building on previous research showing P3H4 overexpression in bladder, lung, and kidney cancers, our study provides the first evidence of P3H4’s crucial role in HCC pathogenesis." (PMID 41220593, 2025).
leukemia (1 paper, 2022). A malignant (clonal) hematologic disorder, involving hematopoietic stem cells and characterized by the presence of primitive or atypical myeloid or lymphoid cells in the bone marrow and the blood. "On the other hand, there were two genes in which overexpression was determined in leukemia-derived cell lines but was not confirmed in patients: COMT and P3H4." (PMID 36428851, 2022).
lung carcinoma (1 paper, 2021). "To explore whether P3H4 regulated the functionalities of lung cancer cells, we silenced the P3H4 gene by two small interface RNAs (siRNAs) using A549 and H1299 cell lines." (PMID 34257701, 2021). "As P3H4 was highly expressed in LUAD, we then explored whether the functionalities of lung cancer cells could be significantly altered by silencing P3H4." (PMID 34257701, 2021).
tumor (15 papers, 2000 to 2025). "Consistently, previous studies also found that P3H4 was involved in regulating the tumor microenvironment and implicated in sensitivity to targeted therapy and immunotherapy." (PMID 34257701, 2021). "The results from the TCGA cohort indicated that P3H4 expression was significantly associated with age, race category, histologic grade, tumor histologic subtype, and AJCC stage (p < 0.05)." (PMID 30322400, 2018). "Western blot analysis of three representative patient sample pairs further confirmed increased P3H4 protein expression in tumor tissues." (PMID 41220593, 2025). "qRT‐PCR measurements demonstrated significantly higher P3H4 mRNA levels in tumor tissues compared to adjacent normal tissues, corroborating our database analyses." (PMID 41220593, 2025). "AP2S1, P3H4 (SC65), SPAG4, PLA2G2F, PTPN6, RAC3, and ETV7 were identified as candidate tumor-associated antigens." (PMID 35814377, 2022). "Our previous studies showed that the expression level of P3H4 was upregulated in BC tumor tissues compared with non-tumor tissues." (PMID 36297587, 2022). "P3H4 was upregulated in primary tumor compared with their paired adjacent normal tissues (2.02 ± 0.64 vs 1.21 ± 0.54, p < 0.001)." (PMID 30322400, 2018). "P3H4 silencing suppresses tumor growth both in vitro and in vivo while simultaneously downregulating key glycolytic enzymes HK2 and LDHA, suggesting a potential metabolic vulnerability that could be therapeutically exploited." (PMID 41220593, 2025). "P3H4 was highly expressed in advanced Tumor, Node and Metastasis (TNM) clinical stages of LUAD." (PMID 35805016, 2022). "The thrombospondins (TSPs) are multifaced proteins and serve as important components of the tumor microenvironment, indicating that P3H4 might be a regulator of tumor microenvironment." (PMID 34257701, 2021). "P3H4 was overexpressed in primary tumor tissues compared with their paired adjacent normal tissues." (PMID 30322400, 2018). "P3H4 might promote LUAD progression through regulating tumor microenvironment-related pathways." (PMID 34257701, 2021). "In total, three potential tumor-specific antigens (AP2S1, P3H4, RAC3) were identified for mRNA vaccine research." (PMID 35814377, 2022). "A xenograft model of BALB/c nude mice was established by implanting A549 cells with sh-circIMMP2L lentivirus and negative control (sh-scramble), and the deletion of P3H4 decreased tumor growth drastically." (PMID 35805016, 2022).
cancer (4 papers, 2018 to 2023). A tumor composed of atypical neoplastic, often pleomorphic cells that invade other tissues. "P3H4 is a key gene that not only regulates malignant progression of various cancers, but also participates in osteoclastogenesis and cell synthesis." (PMID 35805016, 2022). "The prolyl 3-hydroxylase family member 4 (P3H4) is involved in various cancers, but little is known about its role in LUAD." (PMID 35805016, 2022). "Prolyl 3-hydroxylase family member 4 (P3H4) is significantly involved in several types of human cancer." (PMID 30322400, 2018). "A potential biomarker and therapeutic target, P3H4 is involved in various cancers, but its molecular mechanism in LUAD remains unclear." (PMID 35805016, 2022).
P3H4 also shares sentences with these, for which no sentence is quoted: Osteopenia (2 papers); bladder tumor (1); Infertility (1); kidney diseases (1).